MYCN (MYCN proto-oncogene, bHLH transcription factor)
Diseases named in the same sentence as MYCN in open-access papers (continued):
Sharing a sentence is not in itself a finding about the gene and the disease.
neuroblastoma (continued). "Interestingly, circARID1A expression was higher in high-risk neuroblastomas without MYCN amplifications, a subgroup in which molecular pathogenesis is less well understood." (PMID 37402719, 2023). "A 6-year-old girl was referred to our department with a neuroblastoma stadium 4 (high-risk group, MYCN amplification, negative 1p deletion) originating from the right adrenal gland (and the right sympathetic trunk) with encasement of the large abdominal vessels and infiltration of the diaphragm." (PMID 37466795, 2023). "The most frequently harbored alterations of specific genes in neuroblastoma include heritable mutations in the ALK and PHOX2B observed in familial neuroblastoma, chromatin remodeling genes like ATRX, ARID1A and ARID1B and other important genes like PTPN11, MYCN, and NRAS." (PMID 37274289, 2023). "In addition, MYCN was recently shown to promote de novo lipogenesis in neuroblastoma through direct activation of lipogenic enzymes that orchestrate fatty acid synthesis, a key hallmark of metabolic reprogramming in cancer supporting tumor survival under nutrient deprivation conditions." (PMID 37835497, 2023). "The pre-treatment risk stratification for this cancer relies on the International Neuroblastoma Risk Group (INRG) classification system, including age at diagnosis, histologic category, grade of tumor differentiation, tumor cell ploidy, 11q aberration and status of the oncogene MycN." (PMID 36980635, 2023). "To monitor the gene expression in human neuroblastoma and address the impact of MYCN amplification in in vivo metabolic reconstitution, we utilized our established workflow that was previously applied for intratumoral computational transcriptional profiling in neuroblastoma published results." (PMID 37835497, 2023). "Given the critical role of MYCN in the development and progress of high-risk neuroblastoma, there is no doubt that MYCN could be controlled by multiples regulators at the transcriptional and post-translational levels." (PMID 37543638, 2023). "MYCN amplification as a common genetic alteration that correlates with a poor prognosis for neuroblastoma (NB) patients." (PMID 37461251, 2023). "Therefore, targeting BAP1 by its inhibitors such as iBAP-II or in combination with other therapeutic strategies might be an effective treatment strategy for human neuroblastomas with amplified MYCN which warrants further in deep investigation." (PMID 37543638, 2023). "Amplification of MYCN is a significant negative risk factor in neuroblastoma." (PMID 37835416, 2023). "Thus, high MYCN expression in neuroblastomas harboring MYCN amplifications may explain increased footprints of ROS, replication slippage, and stress observed in mutational scenario #1, which was enriched in MYCN-amplified neuroblastomas." (PMID 37868040, 2023). "In neuroblastoma (NB), amplification of the MYCN oncogene and over-expression of MYC characterize approximately 40% and 10% of all high-risk NB cases, respectively." (PMID 37760568, 2023). "In addition, it has been shown that ELOVL4 promotes the differentiation and healthy accumulation of lipids in neuroblastoma cells but is transcriptionally regulated by the MYCN oncogene, which has severe implications on disease outcomes for neuroblastoma patients." (PMID 37513514, 2023). "However, other high-risk neuroblastoma tumors do not harbor either MYCN amplification or mutations in other known tumor drivers, suggesting that perhaps epigenetic changes, such as DNA methylation, are involved in the tumorigenesis process." (PMID 37251933, 2023). "Hence, despite some signs indicating a reliance on glycolytic metabolism, there is a retention of mitochondrial function required for the growth and survival of neuroblastoma, whereby MYCN seems to occupy a position of prominence in controlling both of these major metabolic pathways." (PMID 37414143, 2023).
neuroblastoma (continued). "Therefore, functional interruption of RUNX1 that is causally related to stabilization of TAp63 may potentially contribute to preventing MYCN-driven cell proliferation of neuroblastoma." (PMID 36831211, 2023). "We hypothesized that MYCN-amplified neuroblastomas would have concomitant high XIAP expression." (PMID 37874199, 2023). "Neuroblastoma, accounting for 6% of childhood cancers in the United States, is derived from sympathoadrenal progenitor cells within the neural crest, often develops in and around the adrenal gland, exhibits frequent genetic alterations in MYCN or ALK, and has a 5-year survival rate of 81%." (PMID 37255415, 2023). "Moreover, biomarkers for treatment personalization should be explored, with MYCN amplified neuroblastoma a logical patient population that may benefit." (PMID 37958555, 2023). "However, it remains unknown if IGF2BP1 is an oncogene in human cancers, how it synergizes with MYCN in neuroblastoma and if the targeting of IGF2BP1 harbors therapeutic benefits in cancer treatment." (PMID 37246217, 2023). "Finally, in addition to glutamine, MYCN also controls cysteine addiction in neuroblastoma." (PMID 37414143, 2023). "Targeting KAT2A could provide a new strategy to block MYCN’s oncogenic activity in neuroblastoma." (PMID 37777587, 2023). "Moreover, hijacking enhancers by forming ecDNA could modulate cell viability by regulating oncogene expression, as demonstrated in the case of EGFR in glioblastoma and MYCN in neuroblastoma." (PMID 37448518, 2023). "Given the critical role played by LRP8 and the selenocysteine metabolism in preventing ferroptosis in highly aggressive neuroblastoma subtypes with MYCN amplifications, we addressed whether LRP8 elimination could target neuroblastoma growth by inducing ferroptosis in vivo." (PMID 37435859, 2023). "We next utilized a panel of twelve neuroblastoma cell lines, including MYC- or MYCN-amplified and non-amplified clones, to test whether mitochondrial translation might be a common vulnerability in high-risk neuroblastoma." (PMID 37973789, 2023). "Thus, LRP8 blockade represents a rational strategy to indirectly deplete GPX4 and selectively trigger ferroptosis in MYCN‐amplified neuroblastoma and potentially other entities with low system Xc− expression/activity such as AML and lymphoma, while sparring normal cells." (PMID 37435859, 2023). "Neuroblastoma (NB) is a childhood cancer in which amplification of the MYCN gene is the most acknowledged marker of poor prognosis." (PMID 37623854, 2023). "Therefore, additional studies on the inhibition of LRP8 in immunocompetent models are warranted to fully understand the therapeutic potential of targeting the LRP8/SELENOP axis for therapeutic benefit in neuroblastoma and other malignancies in particular the ones with amplified MYCN." (PMID 37435859, 2023). "Moreover, MYCN directly influences the genetic and epigenetic changes observed in neuroblastoma." (PMID 37444423, 2023). "In addition, a high expression of the transporter was detected in non-small cell lung carcinoma and squamous cell carcinoma (on the protein level), as well as in MYCN-amplified neuroblastoma, colorectal carcinoma and urothelial bladder carcinomas (on the mRNA level)." (PMID 36839686, 2023). "TP73 could regulate the expressions of MYCN and induce the differentiation of neuroblastoma." (PMID 37904225, 2023). "However, to study neuroblastoma disease in vivo, several mouse models have been developed through genetic engineering, the TH-MYCN transgenic mouse model (which expresses human MYCN specifically in neuroblasts under the control of the tyrosine hydroxylase (TH) promoter) being the most widely used." (PMID 36675105, 2023). "In addition, another study revealed that high expression of 4EBP1 is closely related to poor prognosis in neuroblastoma via MYCN upregulation, and may confer advantages to tumor cell survival and proliferation under nutrient deprivation and metabolic stress." (PMID 36944636, 2023).
neuroblastoma (continued). "However, we did not observe this association, which might be explained by the low number of neuroblastomas in our cohort (n = 20 samples, of which 6 are MYCN-amplified)." (PMID 36702933, 2023). "Finally, we showed that a nomogram risk model based on age, MYCN amplification and ZNF436 could predict the overall survival of neuroblastoma with high specificity and sensitivity." (PMID 37904225, 2023). "A confounding bias was unlikely in the reanalysis of the dataset of patients affected by Stage 4S neuroblastoma because the analysed patients were quite homogeneous for the major known prognostic factors, including age at diagnosis, stage, and amplification of the MYCN proto-oncogene." (PMID 36831529, 2023). "We discovered that MYCN-amplified neuroblastoma (NB) tumors have high levels of TfR1 and low levels of FPN, contributing to increased cellular iron levels." (PMID 35174317, 2022). "LMO1 is implicated as an independent predictor of poor patient survival in the clinic and its co-expression with MYCN was associated with an earlier onset and increased penetrance of neuroblastoma, indicating that the inhibition of MYCN might lead to a concomitant decrease of LMO1." (PMID 35805002, 2022). "In addition to neuroblastoma, increased MYCN activation, mainly through genomic amplification, is commonly observed in neuronal and neuroendocrine cancers, including medulloblastoma, Wilms tumor, retinoblastoma, neuroendocrine prostate cancer, glioblastoma, and small-cell lung cancer." (PMID 36077650, 2022). "Since many enzyme-encoding genes are actively transcribed in cells for the maintenance of basic metabolic functions, it is reasonable to speculate that the MYCN-driven global transcriptional amplification could have a profound impact on metabolic reprogramming in neuroblastoma cells." (PMID 36077650, 2022). "In addition to enhancing glutamine transport and glutaminolysis, MYCN may promote glutamine synthesis in neuroblastoma cells." (PMID 36077650, 2022). "Based on the patient’s age at diagnosis, tumor stage and MYCN amplification, NB cases are classified into a low-, intermediate-, or high-risk group following the International Neuroblastoma Risk Group (INRG)." (PMID 36092735, 2022). "Interestingly, besides MYCN amplification that is a bad prognosis factor in neuroblastoma, a recent study found that transcription of five genes including CCL19 and CD1C, could predict better prognosis." (PMID 36923280, 2022). "International Neuroblastoma Staging System (INSS), Children’s Oncology Group (COG), and MYCN amplification have been used clinically to determine the treatment plan and predict prognosis for NB patients." (PMID 35401536, 2022). "Neuroblastoma is a deadly childhood cancer, and MYCN-amplified neuroblastoma (MNA-NB) patients have the worst prognoses and are therapy-resistant." (PMID 35490242, 2022). "Although our analysis of the entire high-risk neuroblastoma cohort identified a cluster associated with MYCN amplifications, no clinically meaningful subgroup with prognostic relevance could be identified." (PMID 36319669, 2022). "To test whether inhibition of retrotranspositions has an anticancer effect, we used treatment with the nucleoside reverse transcriptase inhibitor (NRTI) stavudine (STV) in mouse cancer models, MMTV-HER2/Neu and Th-MYCN, that spontaneously develop breast cancer and neuroblastoma, respectively." (PMID 36449545, 2022). "It is reported that CAMKV could as an immunotherapeutic target for MYCN amplified neuroblastoma." (PMID 36158685, 2022). "Other than the direct action of MYCN on cellular process leading to neuroblastoma, in the past few years, many epigenetic mechanisms have been discovered regulating MYCN with a specific role in HR-NB development." (PMID 36139583, 2022).
neuroblastoma (continued). "To further clarify whether bub1 expression was simply a coeffect of other risk factors such as MYCN amplification in predicting neuroblastoma survival, we divided patients into groups with or without MYCN amplification." (PMID 36237324, 2022). "Since miR-202 was a strong negative regulator of MYCN expression, a strategy for neuroblastoma treatment further research has to reveal whether targeting of the MYCN axis by instigating the expression of miR-202 is an option for neuroblastoma treatment." (PMID 35682549, 2022). "We next examined whether DHODH dependency correlates with MYCN dependency in neuroblastoma." (PMID 35943801, 2022). "MYCN amplification occurs in almost 25% of all neuroblastoma cases and correlates with HR-NB and poor prognosis." (PMID 36139583, 2022). "An in vitro study on neuroblastoma cells with and without MYCN amplification showed that treatment with specific anti-MYCN small interfering RNAs (siRNAs) targeting the MYCN mRNA may cause cell growth arrest, the activation of apoptosis, and differentiation." (PMID 36139583, 2022). "The aim of this study was to investigate whether 11q loss of heterozygosity (LOH) aberration would impact the response of the primary tumor to neoadjuvant chemotherapy or to the degree of surgical resection in neuroblastoma (NB) patients with MYCN amplification." (PMID 35757140, 2022). "ASCL1 and other developmental regulators of neurogenesis form an aberrant ‘core regulatory circuit’ (CRC), that promotes oncogenicity of neuroblastoma cells, where mutually regulated high levels of expression of the circuit genes is usually reinforced by elevated MYCN." (PMID 36263020, 2022). "In addition, several studies proved that inhibiting mTOR signaling to further downregulate cellular protein synthesis could deregulate MYCN-driven proliferation, suggesting that mTOR pathway is another key factor in MYCN-amplified children neuroblastoma." (PMID 35805002, 2022). "The International Neuroblastoma Risk Group (INRG) classification system defines the prognosis of NB by various factors at diagnosis: age, histopathological classification, degree of tumor differentiation, amplification of MYCN oncogene, DNA ploidy, and presence of segmental chromosome aberrations." (PMID 35742955, 2022). "Moreover, JQ1 could induce cell cycle arrest in MYCN-amplified neuroblastoma in vitro and block tumor growth in vivo by inhibiting MYCN expression." (PMID 36187481, 2022). "In the solid tumors, there was a reduction in microvascularity and signs of increased hemorrhage, which might reflect collapse of tumor vasculature previously observed in the Omomyc tumor model after MYC inhibition and after MYCMI-6 treatment in a MYCN-amplified neuroblastoma xenograft mouse model." (PMID 36874405, 2022). "Notably, almost 30% of neuroblastoma patients show the MYCN amplification." (PMID 33430027, 2021). "Lately, these methods have been coupled with strategies targeting specific oncogenic drivers of neuroblastoma, including MYCN, ALK, and TrkB, that are associated with HR-NB, and novel treatment strategies are currently being investigated." (PMID 34204830, 2021). "Here, a case of neuroblastoma (NB) carrying a high-grade amplification of six loci besides MYCN is described." (PMID 34830942, 2021). "Interestingly, high expression levels of ALCAM, CACNA2D3, DST, EPB41L4A or KIF1B were not only associated with the prognosis of MYCN non-amplified neuroblastoma patients, but also were associated with the prognosis of all neuroblastoma patients." (PMID 34116676, 2021). "In summary, ZRF1 mRNA levels are associated with poor prognosis in neuroblastoma and may be used as an independent prognostic marker in the absence of MYCN amplification and other poor prognosis-related chromosomal aberrations." (PMID 34638328, 2021).
neuroblastoma (continued). "Moreover, in the remaining 50% of high-risk neuroblastoma patients without tumor MYCN amplification, the lack of a unified oncogenic driver makes the design of novel therapies a challenge." (PMID 35198433, 2021). "Interestingly, R9-caPep is most effective on MYCN overexpressed neuroblastoma cells." (PMID 33498235, 2021). "Indeed, such events in 11q-deletion can be further impacted on by deregulated oncogenic activities, such as MYCN amplification and aberrant ALK/MAPK signaling, resulting in normal cell development veering off-track and promoting evolution of high-risk neuroblastoma." (PMID 34885007, 2021). "The International Neuroblastoma Risk Group (INRG) has developed a classification system for neuroblastoma risk stratification based on clinical criteria, including stage, histology, differentiation, ploidy, alterations at chromosome 11q, and amplification of MYCN." (PMID 34440719, 2021). "For example, miR-15a-5p, miR-15b-5p, and miR-16-5p were reported to inhibit NB progression by directly targeting Neuroblastoma MYC Oncogene (MYCN)." (PMID 34889712, 2021). "The presence of either a chromosome 1p deletion, and/or a chromosome 11q deletion, and/or a 17q gain was associated with poorer OS according to a multivariate survival analysis, suggesting that these particular mutations are important for patients with MYCN non-amplified neuroblastomas." (PMID 34069817, 2021). "In addition to SCLC, ∼20% of MYCN-amplified neuroblastoma cells are highly sensitive to Venetoclax." (PMID 34581776, 2021). "Moreover, MYCN amplification represents a therapeutic target in neuroblastoma." (PMID 34116676, 2021). "ARMC6 is the target gene of MYCN and indicates a poor prognosis for patients with neuroblastoma (NB)." (PMID 34912852, 2021). "Neuroblastoma (NB) patients with MYCN amplification or overexpression respond poorly to current therapies and exhibit extremely poor clinical outcomes." (PMID 34565342, 2021). "Thus, ALYREF is a transcriptional target of MYCN in MYCN-amplified neuroblastoma cells." (PMID 33767157, 2021). "Besides MYCN amplification, age at initial neuroblastoma diagnosis is also a prognostic factor." (PMID 34116676, 2021). "Therefore, vaccination against CEP55 might be an avenue for further research in MYCN‐driven neuroblastoma." (PMID 33497018, 2021). "Since age associated gene DST was an independent prognostic factor in MYCN non-amplified pediatric neuroblastoma, we wondered if the combination of DST, age and MYCN could achieve the best prognostic significance." (PMID 34116676, 2021). "Therefore, the impact of the genotype on ODC1 expression in neuroblastoma may depend on the balance of MYCN levels and MAD1/MXI1 levels, and their binding with MAX." (PMID 33918978, 2021). "Over the past two decades, the International Neuroblastoma Risk Group (INRG) classification system has defined a unified approach for pretreatment assessment, which includes age at diagnosis, histology, the grade of tumor differentiation, MYCN status, 11q aberration, and ploidy." (PMID 33767996, 2021). "TrkA and TrkC high expression are favorable prognostic markers in neuroblastoma, in association with a differentiated phenotype and absence of MYCN amplification, whereas high TrkB expression associates with aggressive neuroblastomas and chemotherapy resistance." (PMID 34957126, 2021). "In addition, neuroblastoma-bearing MYCN transgenic zebrafish at 0.5–1.5 years of age overexpressing dβh:EGFP-MYCN, were treated with 2 μl of vehicle (100% DMSO), 1 μl of SAHA (21 mg/kg), 1 μl of SE486-11 (30 mg/kg), or 1 μl of SAHA plus 1 μl of SE486-11 by oral gavage." (PMID 33658627, 2021). "Thus, the combination of VMAT inhibitor with COMT/MAO inhibitor (MYCN-cluster) or MIBG radiation therapy (ATRX-cluster) might be a potential therapeutic strategy for treating neuroblastoma cases." (PMID 33465163, 2021). "No pathway‐specific polygenic scores were associated with MYCN‐amplified neuroblastoma risk." (PMID 32945147, 2020).